LINC02611 (long independently transcribed non-coding RNA 2611)
Gene: Long non-coding RNA gene on chromosome 2 (98,761,098 to 98,775,361, reverse strand). Ensembl gene ENSG00000226791.
Diseases named in the same sentence as LINC02611 in open-access papers:
LINC02611 is named in the same sentence as 1 disease in open-access papers, as found by Europe PMC text mining. Sharing a sentence is not in itself a finding about the gene and the disease. The quoted sentences say what the papers report.
tumor (1 paper, 2023). "LINC00944, LINC02611, PRKAR1B-AS1, LINC02328 and LINC02100 were expressed at higher levels in ccRCC tumor tissues compared to that in normal tissues, which was consistent with the results of the TCGA-ccRCC cohort." (PMID 37415739, 2023).